PBRM1 (polybromo 1)
Diseases named in the same sentence as PBRM1 in open-access papers (continued):
Sharing a sentence is not in itself a finding about the gene and the disease.
renal cell carcinoma (51 papers, 2013 to 2026). "By contrast, PBRM1 loss in renal cell carcinoma is associated with primary ICIs resistance, and ARID1A deficiency in gastric cancer promotes aggressive metastatic behavior." (PMID 41438758, 2025). "For instance, loss of ARID1A or ARID1B confers enhanced response to immune-checkpoint blockade (ICB) in melanoma and non-small cell lung cancer, whereas PBRM1 deficiency promotes primary resistance in renal cell carcinoma." (PMID 41438758, 2025). "Emerging biomarkers such as gene expression profiles and the loss of pro-angiogenic proteins VHL and PBRM-1 show promise for identifying renal cell carcinoma cases likely to respond to ICI." (PMID 37568390, 2023). "Preclinical evidence suggests that, in renal cell carcinoma, PBRM1 mutations are a synthetic lethal target of PARPi and ATRi11." (PMID 37400502, 2023). "The mutation rate of VHL in renal cell carcinoma was the highest, followed by PBRM1, TTN, and SETD2." (PMID 36186476, 2022). "The alteration of the expression levels of PBRM1 was associated with the development of both renal cell carcinoma and MM." (PMID 34834557, 2021). "PBRM1 (also known as BAF180) mutation is observed in approximately 40% of renal cell carcinomas (RCC) and also in a small number of breast cancers." (PMID 34671561, 2021). "PBRM1 GA linked in some studies to benefit from ICPI in renal cell carcinoma were found in only in 1% of CA-Pheo and 2% of CA-Para." (PMID 34282751, 2021). "Low PBRM1 expression has been shown to predict poor prognosis in breast cancer and mutations in PBRM1 have been reported in many tumor types such as renal cell carcinoma, biliary carcinoma, gallbladder carcinoma, and intrahepatic cholangiocarcinoma." (PMID 31430859, 2019). "Recently, PBRM1 had been demonstrated to exert tumor suppressing properties owing to its frequent mutations in various cancer types, including renal cell carcinomas and breast cancer." (PMID 25978027, 2015). "In comparison, PBRM1 is 3.8–7.4 times more frequently mutated in (26.62%) [27.5%] renal cell carcinomas than in these other tumor types." (PMID 25774356, 2014). "In contrast, PBRM1 involvement in 3p21 loss of heterozygosity in renal cell carcinoma is well documented and correlates with frequent mutations in PBRM1 in this tumor." (PMID 25774356, 2014). "Indeed, the synthetic lethal effect of poly-(ADP-Ribose) polymerase (PARP) inhibitors (PARPi) has been suggested in an in vitro renal cell carcinoma model harboring PBRM1 mutations." (PMID 37400502, 2023). "PBRM1, a target subunit of PBAF, is a common oncogene with a 40% mutation rate in renal cell carcinoma, and our previous study found that deletion of PBRM1 could activate the AKT pathway and glycolytic pathway and thus affect the function of ccRCC cells." (PMID 36883311, 2023). "PBRM1 is frequently mutated in renal cell carcinoma and drives carcinogenesis." (PMID 36362284, 2022). "PBRM1 gene mutation is closely related to the occurrence and development of renal cell carcinoma." (PMID 35368029, 2022). "Likewise, the rate of abrogating mutations in PBRM1 is (21.1%) [22.5%] out of a total mutation rate of (26.6%) [27.5%] in renal cell carcinomas as indicated in the TCGA and Cosmic databases." (PMID 25774356, 2014). "In renal cell carcinoma, tumors with PBRM1 deletion exhibit increased replication stress, DNA double-strand breaks, and genomic instability." (PMID 41440218, 2025). "This study found that Polybromo‐1 (PBRM1) sensitizes renal cell carcinoma (RCC) to immunotherapy through regulating macrophage‐associated chemokines and increasing M1 macrophage infiltration." (PMID 39656940, 2025).
renal cell carcinoma (continued). "In contrast, acetylation of H3K14 was reported as crucial for tumor suppressor functions of polybromo-1 (PBRM1) in the 786-O kidney cancer cell line (renal cell carcinoma)." (PMID 39456765, 2024). "In a small renal cell carcinoma study, loss of function mutation in one component of the SWI/SNF (PBRM1) complex, demonstrated a better response to anti-PD-L1 therapy." (PMID 36845691, 2023). "For instance, PBRM1, which encodes the BAF180 subunit of SWI/SNF, is frequently lost in renal cell carcinoma (RCC)." (PMID 37415185, 2023). "The most obvious of these, PBRM1, has previously been shown from patient samples in renal cell carcinoma to impact outcomes to checkpoint blockade and has been demonstrated to augment T cell-mediated killing." (PMID 33106165, 2020). "In a clinical trial of renal cell carcinoma patients treated with anti-PD1 or anti-PD-L1 alone, or in combination with anti-CTLA4, PBRM1 mutation is related with a higher ORR and longer survival." (PMID 33409155, 2020). "Biomarkers of response previously explored include angiopoietin-2 (ANGPT2) in melanoma and polybromo-1 (PBRM1) and polybromo-associated barrier-to-autointegration factor (PBAF) in renal cell carcinoma (RCC)." (PMID 31464611, 2019). "In a mouse model of renal cell carcinoma, PBRM1 influenced the growth of tumors in nude mice subcutaneously injected with ACHN cells." (PMID 28846693, 2017). "PBRM1 is a novel tumor suppressor gene that can inhibit cancer cell proliferation and predict the outcome of renal cell carcinoma (RCC), but its biological role needs further elucidation." (PMID 28846693, 2017). "Recently, the SWI/SNF complex subunit PBRM1 has been suggested to exert its tumor suppressive functions in renal cell carcinoma and breast cancer." (PMID 25978027, 2015). "They revealed the mutation of ARID1A, which codes BAF250a protein, in about half of ovarian clear cell carcinomas, and PBRM1, which codes BAF180, in approximately 40% of renal cell carcinomas." (PMID 23229642, 2013). "Recently, it was reported that PBRM1-mut renal cell carcinoma shows sensitivity to PARPi11." (PMID 37400502, 2023). "Here, we aimed to explore whether the ubiquitination modification of PBRM1 was also presented in renal cell carcinoma cells." (PMID 35368029, 2022). "PBRM1 could regulate renal cell carcinoma proliferation and cell cycle through the chemokine/chemokine receptor interaction pathway." (PMID 36397762, 2022). "In comparison, the loss of PBRM1 is between 53 and 70% from the published IHC data, which suggests that mutations are not the only mechanism underlying PBRM1 silencing in renal cell carcinomas." (PMID 25774356, 2014). "In renal cell carcinoma (RCC), for example, a panel of mRNA markers (CUL9, KMT2D, PBRM1, PREX2, and SETD2) has been identified as a highly accurate classifier, distinguishing RCC from benign renal masses with an AUC of 0.83." (PMID 40149276, 2025). "Furthermore, changes in PBRM1 have been confirmed to be a reliable indicator of the immune checkpoint inhibitor response in renal cell carcinoma (RCC)." (PMID 39136020, 2024). "Genomic studies identifying the genes for kidney cancer, including the VHL, PBRM1, MET, FLCN, fumarate hydratase, succinate dehydrogenase, TSC1, TSC2, and TFE3 genes are known to play role in renal cell carcinoma development." (PMID 35709632, 2022). "The impact of Polybromo-1 (PBRM1) on TME and response to ICB in renal cell carcinoma (RCC) remains to be resolved." (PMID 32358509, 2020). "For example, a multi-region sequencing analysis identified inactivation of Polybromo 1 (PBRM1), a component of the SWI/SNF (SWItch/Sucrose Non-Fermentable) chromatin remodeling complex, as a truncal event in several renal cell carcinoma cases." (PMID 29104272, 2017).
renal carcinoma (45 papers, 2012 to 2026). A carcinoma arising from the epithelium of the renal parenchyma or the renal pelvis. "We showed that BAP1 gene mutation plus wild type PBRM1 had significant contributions to renal cancer PFS and DFS." (PMID 37515929, 2023). "Our data reveal that mutation of the nucleic acid binding pocket decreases PBRM1 affinity for chromatin and inhibition of Caki2 renal carcinoma cell proliferation." (PMID 36808431, 2023). "While the majority of PBRM1 mutations in renal cancers result in loss of protein expression, a subset of PBRM1-mutant tumors (∼15%) have missense mutations that cluster across the bromodomains." (PMID 36808431, 2023). "Next-generation sequencing revealed that PBRM1 is the second most highly mutated gene in renal cancer." (PMID 35368029, 2022). "PBRM1 loss has been implicated in responses to immunotherapy in renal cancer, but the mechanism is unclear." (PMID 35902118, 2022). "Together, our data demonstrated that Fdcyd treatment induced synthetic lethality in PBRM1-deficient renal cancer in vivo." (PMID 35719970, 2022). "PBRM1 mutation is known to be closely related to the high angiopoiesis level in renal cancer, and PBRM1 mutations reduce the clinical benefit of immune checkpoint blocking therapy in RCC." (PMID 36060659, 2022). "For instance, PBRM1 is the second largest mutation gene in renal cancer, while the mutation event of PBRM1 in the two renal cancer subtypes described herein presented inconsistent survival benefits for the patients." (PMID 35028006, 2022). "Intriguingly, this PBRM1 mutation is associated with the therapeutic effect of ICIs in renal cancer." (PMID 34359568, 2021). "PBRM1-deficient renal cancers show altered transcriptional expression in the JAK/STAT (Janus kinase/signal transducers and activators of transcription) and immune signaling pathways." (PMID 34359568, 2021). "Genetic abnormalities in SWI/SNF complex subunits are frequently observed in HCC and other human tumors, and loss-of-function mutations in the polybromo 1 (PBRM1) gene involved in the SWI/SNF complex are common in renal cancer." (PMID 34359568, 2021). "Of note, PBRM1 is often mutated in renal cancer, where the HIF system plays an important role in the oncogenic process." (PMID 34200988, 2021). "Understanding the contribution of PBRM1 dysregulation and its associated pathways to clinical disease progression and outcome are important future areas of renal cancer research." (PMID 28846693, 2017). "Certain subunits are highly mutated in specific cancers such as the following: PBRM1 (BAF180) is mutated in liver and renal carcinoma, while ARID1A is preferentially mutated in uterine, cervical, ovarian and gastric cancers." (PMID 28105458, 2016). "Notably, increased FBXW7 mutations were observed in patients of African descent, while VHL and PBRM1 mutations were decreased in African-origin renal cancer patients." (PMID 40564200, 2025). "We further tested this using a panel of six renal cancer cell lines, in which three have loss of function mutations in PBRM1, and we found that PBRM1 deficient cells are considerably more sensitive to CCNB1 depletion than the PBRM1 proficient cell lines, suggesting potential clinical implications." (PMID 40011561, 2025). "In renal cancer, there are two other common subtypes, characterized by PBRM1 and BAP1 mutations." (PMID 39119581, 2024).
renal carcinoma (continued). "In summary, results of our in vitro and mouse xenograft in vivo studies indicated that Fdcyd treatment was synthetic lethal with PBRM1 loss in ccRCC and Fdcyd could serve as a novel therapeutic agent for renal cancer with PBRM1 deficiency." (PMID 35719970, 2022). "This may be attributed to the tissue-specificity of PBRM1 function and may explain why most PBRM1 mutations are found in renal cancer." (PMID 31863007, 2019). "This study identifies alternative splicing of PBAF SWI/SNF chromatin remodeller subunit PBRM1 as a control factor for response to PD-1 blockade therapy in renal cancer." (PMID 39375538, 2024). "We validated these findings at the cellular level, employing lentiviral transduction to express full-length PBRM1 WT and select PBRM1-BD4 missense variants in renal cancer cells." (PMID 38460939, 2024). "In renal cancer, SETD2 mutations are frequently associated with VHL, PBRM1, and BAP1 mutations as a result of chromosome 3p21 deletion." (PMID 37528416, 2023). "Based on an analysis of 79 genes associated with renal cancer, we found that VHL, PBRM1, BAP1, SETD2, and TSC1 mutation rates were higher in all RCCs at 51%, 35%, 16%, 15%, and 13%, respectively." (PMID 37427096, 2023). "As reported in our review, the most common somatic gene mutations in renal cancer are related to VHL, PBRM1, BAP1, and SETD2, although a relatively small number of other mutated genes are reported to be involved in kidney cancer." (PMID 36902045, 2023). "This indicates that mutation in nucleic acid binding residues of BD2 and BD4 affects the growth suppressive function of PBRM1 in renal cancer cells." (PMID 36808431, 2023). "PBRM1 is a confirmed tumor suppressor when deleted with VHL in mouse models of renal cancer; however, PBRM1 deletion in most cells leads to either no change or context-dependent effects on growth rates." (PMID 36808431, 2023). "Meanwhile, we also showed that the protein level of UBE3A was negatively correlated with the PBRM1 protein level in the renal cancer patient specimens." (PMID 35368029, 2022). "In summary, our results demonstrate that the RBPJ/DAPK3/UBE3A/PBRM1/p21 signaling pathway regulated the sensitivity of renal cancer cells to CDK4/6 inhibitors." (PMID 35368029, 2022). "Taken together, these data suggest that RBPJ acts as a transcription factor of DAPK3 and regulates PBRM1 in renal cancer cells." (PMID 35368029, 2022). "In this study, we performed unbiased mass spectrometry of PBRM1 and identified ubiquitin-protein ligase E3A (UBE3A), a well-known E3 ligase, that can bind with PBRM1 and regulate the stability of PBRM1 in renal cancer cells." (PMID 35368029, 2022). "In summary, we not only revealed a novel RBPJ/DAPK3/UBE3A/PBRM1/p21 signaling axis but also identified a combination strategy for overcoming the resistance of renal cancer cells to CDK4/6 inhibitors." (PMID 35368029, 2022). "In summary, we demonstrated that UBE3A functions as a newly found E3 ligase of PBRM1 in renal cancer cells." (PMID 35368029, 2022). "Together, these data suggest that DAPK3 is a binding partner of UBE3A and critical for PBRM1 degradation in renal cancer cells." (PMID 35368029, 2022). "In this study, we performed unbiased mass spectrometry of PBRM1 and identified ubiquitin-protein ligase E3A (UBE3A), an extensively studied E3 ligase that can bind with PBRM1 and regulate the stability of PBRM1 in renal cancer cells." (PMID 35368029, 2022).
renal carcinoma (continued). "The α and β breakpoints fall within exons of the NISCH gene while the γ breakpoint falls within exon 27 of PBRM1, a gene previously shown to be a cancer driver in renal carcinoma and intrahepatic cholangiocarcinomas." (PMID 33823910, 2021). "PBRM1, a component of the chromatin remodeller SWI/SNF, is often deleted or mutated in human cancers, most prominently in renal cancers." (PMID 34200988, 2021). "Although much effort has been devoted to understanding the PBRM1 function in renal cancer, only incipient information regarding its role in PCa is available." (PMID 31212728, 2019). "Alterations in the PBRM1 gene have been described in approximately 2–14% of breast cancers and 40% of renal cancers." (PMID 31212728, 2019). "The SWI/SNF complex has been implicated in malignant rhabdoid tumors, and specific subunits of this complex (SNF5/SMARCB1, SMARCE1, BRG1, PBRM1/BAF180) have been identified in approximately 20% of human cancers including renal carcinoma, and NSCLC." (PMID 29988316, 2018). "We found that classic renal cancer–related genes such as VHL, PBRM1, TTN, and SETD2 had higher mutation frequencies in the TCGA-KIRC cohort, with PBRM1 having a higher mutation rate in XPS1 compared to XPS2 (43% vs. 37%), while mTOR had a lower mutation rate in XPS1 compared to XPS2 (6% vs. 10%)." (PMID 39882192, 2025). "Therefore, a peptide named PB1‐p62 was designed to target PBRM1 and p62, resulting in the degradation of most of PBRM1 via autophagy and notably ensuring the efficacy of immunotherapy for renal cancer." (PMID 39656940, 2025). "Some researchers have reported that PBRM1 loss defines a non-immunogenic tumor phenotype associated with checkpoint inhibitor resistance in renal carcinoma." (PMID 37427096, 2023). "Moreover, the RBPJ/DAPK3/UBE3A/PBRM1/p21 axis induced increased sensitivity of renal cancer cells to CDK4/6 inhibitors." (PMID 37385985, 2023). "Therefore, our results indicate that DAPK3 competes with PKA to bind with UBE3A and enhances the degradation of PBRM1 in renal cancer cells." (PMID 35368029, 2022). "Finally, we demonstrated that the RBPJ/DAPK3/UBE3A/PBRM1/p21 axis contributed to the sensitivity of renal cancer cells to CDK4/6 inhibitors." (PMID 35368029, 2022). "To explore whether DAPK3 destabilized PBRM1 through UBE3A in renal cancer cells, we performed knockdown of DAPK3 and UBE3A alone or in combination in 786-O and ACHN cells." (PMID 35368029, 2022). "Therefore, we not only revealed a novel RBPJ/DAPK3/UBE3A/PBRM1/p21 axis but also identified a combination strategy for overcoming the resistance of renal cancer cells to CDK4/6 inhibitors." (PMID 35368029, 2022). "Moreover, our data suggest that the RBPJ/DAPK3/UBE3A/PBRM1/p21 axis modulated the sensitivity of renal cancer cells to CDK4/6 inhibitors." (PMID 35368029, 2022). "Besides, we also showed that PBRM1 silencing promoted renal cancer cells proliferation, which overexpressed PBRM1 inhibited the cancer cells' growth in vitro." (PMID 35368029, 2022). "In contrast, overexpressed PBRM1 sensitized renal cancer cells to CDK4/6 inhibitors." (PMID 35368029, 2022). "We found that the knockdown of UBE3A increased the PBRM1 protein level in renal cancer cells." (PMID 35368029, 2022). "Our results illustrate how VHL and PBRM1 co-operate to drive renal transformation and uncover replication stress as an underlying vulnerability of all VHL mutated renal cancers that could be therapeutically exploited." (PMID 29229903, 2017). "Thus, the rationalized design of chimeric peptides targeting the degradation process may greatly reduce the level of PBRM1 in renal cancer and improve the efficacy of immunotherapy." (PMID 39656940, 2025).